MIR4726 (microRNA 4726)
Synonyms: hsa-mir-4726
Gene: MicroRNA gene on chromosome 17 (38,719,691 to 38,719,748, forward strand). Ensembl gene ENSG00000273627.
Homologues: Orthologues: chimpanzee MIR4726 (100% identical).